MB (myoglobin)
Diseases named in the same sentence as MB in open-access papers (continued):
Sharing a sentence is not in itself a finding about the gene and the disease.
hyperuricemia (4 papers, 2020 to 2023). An abnormally high level of uric acid. "Hyperuricemia group had higher levels of TG and myocardial biomarkers such as myoglobin and NTproBNP compared with the normuricemia group (all P <0.05)." (PMID 34568374, 2021).
Hypokalemia (4 papers, 2015 to 2026). An abnormally decreased potassium concentration in the blood. "Hypokalemia-induced muscular ischemia may increase the permeability of cell membrane, raising the intracellular calcium concentration to destroy myofibrillar, cytoskeletal and membrane proteins, thus leading to muscle necrosis and intracellular CK and myoglobin released into the blood circulation." (PMID 37131142, 2023).
melanoma (4 papers, 1989 to 2022). A malignant, usually aggressive tumor composed of atypical, neoplastic melanocytes. "Hematolymphoid markers (CD45, B cell, and T cell), myogenic markers (myoglobin, desmin, myogenin), melanoma markers (HMB 45, melan A, tyrosinase) and Ewing’s sarcoma markers (CD99/MIC2) are absent in most ONB cases." (PMID 36452830, 2022). "This was performed by reacting a large number of tumours (sarcomas, carcinomas and melanomas) with a polyclonal anti human myoglobin antiserum." (PMID 2757915, 1989). "However, staining for myoglobin, desmin, MSA, SMA, human melanoma, black-45 (HMB-45) and CD99 are often negative, which is consistent with the present case." (PMID 23761028, 2013).
metabolic acidosis (4 papers, 2009 to 2025). "The need for CPR, lower GCS scores, severe metabolic acidosis characterized by low pH and elevated lactate levels, and increased concentrations of myoglobin, CK-MB quotient, and blood glucose on admission were significantly associated with in-hospital mortality." (PMID 41283479, 2025).
myeloma (4 papers, 2020 to 2025). "These proteins are often immunoglobulin light chains (i.e., Bence Jones proteins), in multiple myeloma but also lysozyme, myoglobin or free hemoglobin can be seen." (PMID 40603713, 2025). "These casts cause tubular obstruction and toxicity in a manner akin to that of myeloma or myoglobin casts." (PMID 34514566, 2021).
respiratory failure (4 papers, 2013 to 2024). The significant impairment of gas exchange within the lungs resulting in hypoxia, hypercarbia, or both, to the extent that organ tissue perfusion is severely compromised. "Studies have shown that myoglobin is a predictive indicator of mortality and risk of deterioration in coronavirus disease 2019 (COVID-19) patients with respiratory failure." (PMID 38355552, 2024). "Severe pulmonary involvement and higher levels of CRP, IL-6, D-dimer, AST, creatinine, myoglobin, and lower levels of Tlymp, Hb, and 25(OH)D were associated with respiratory failure." (PMID 35172759, 2022). "Serial monitoring for hyperthermia, cardiovascular collapse, acute myoglobin-induced renal failure, respiratory failure, and aspiration pneumonia is critical." (PMID 23853728, 2013). "Our results confirm that serum myoglobin levels may be useful in understanding the progression of critical illness, particularly in predicting readmission due to respiratory failure." (PMID 38355552, 2024). "Similarly, the association between myoglobin and readmission in patients with respiratory failure has not been studied." (PMID 38355552, 2024). "Laboratory values that can help diagnose these conditions are high levels of neutrophils, C-reactive protein (CRP), troponin, myoglobin, d-dimer, lactate dehydrogenase (LDH), and IL-6; these parameters and low lymphocyte counts predict progression to respiratory failure and death." (PMID 35172759, 2022).
acute respiratory distress syndrome (3 papers, 2010 to 2025). Progressive and life-threatening pulmonary distress in the absence of an underlying pulmonary condition, usually following major trauma or surgery. "On the next day his temperature was 40.7°C, heart rate 156 beats/min and blood pressure 113/61 mmHg; he was diagnosed with acute respiratory distress syndrome (ARDS), acute renal failure, rhabdomyolysis with repeat CK levels of 12516 U/L and urinary myoglobin levels 936000 μg/L (n = up to 1000)." (PMID 20193067, 2010).
Anxiety (3 papers, 2025 to 2026). Intense feelings of nervousness, tension, or panic often arise in response to interpersonal stresses. "The MBC protocol emphasizes hyperthermia and increased urine myoglobin, sensitivity to contextual reminder (noise), and a trend towards anxiety, particularly in females, highlighting sex-specific physiological responses." (PMID 40119337, 2025). "For anxiety, vitamin D and myoglobin were important biomarkers in men, while IL-8 and vitamin D were key in women." (PMID 40563433, 2025). "For anxiety, the most relevant biomarkers were IL-8 and vitamin D. In the male group, interactions for depression occurred among vitamin D, CRP, and D-dimer, while for anxiety, the key biomarkers were vitamin D, myoglobin, and D-dimer." (PMID 40563433, 2025).
atherosclerosis (3 papers, 2014 to 2024). A disease characterized by the build-up of fatty material and calcium deposition in the arterial wall resulting in partial or complete occlusion of the arterial lumen. "Additionally, myoglobin may be involved in the recruitment and activation of immune cells, such as macrophages, which play a role in the inflammatory response associated with atherosclerosis." (PMID 38396639, 2024). "The exact mechanisms by which myoglobin influences atherosclerosis are not fully understood, and research in this area is ongoing." (PMID 38396639, 2024). "Men had higher concentrations of biomarkers reflecting cardiomyocyte necrosis (i.e. myoglobin) and the promotion of atherosclerosis (i.e. matrix metalloproteinase-3)." (PMID 33831096, 2021).
cardiomyopathy (3 papers, 2018 to 2023). A disease of the heart muscle or myocardium proper. "Based on gene expression and histology, clusters 0, 2, and 4 are skeletal muscle due to the high expression of APOD, MB, TCAP, and TNNC2 with significant upregulation of contractile components and cardiomyopathy processes." (PMID 37370820, 2023). "As cardiomyopathy is usually the major defined characteristic of DD11, and Lamp2y/− rats displayed damage to the myocardium with increased serum troponin I, myoglobin and CK, we first assessed the cardiac status of Lamp2y/− rats." (PMID 29720683, 2018).
colorectal cancer (3 papers, 2016 to 2024). A primary or metastatic malignant neoplasm that affects the colon or rectum. "Intake of red meat is considered a risk factor for colorectal cancer (CRC) development, and heme, the prosthetic group of myoglobin, has been suggested as a potential cause." (PMID 27806694, 2016). "The anti-myoglobin Affimer was used as a negative control because colorectal cancer cells do not express this human cardiac muscle-related protein." (PMID 38506227, 2024).
Depression (3 papers, 2024 to 2026). "On discharge, the depressive syndrome was completely remitted and CK, CK-Mb, myoglobin and liver enzymes were normal." (PMID 39143959, 2024).
Disseminated intravascular coagulation (3 papers, 2022 to 2026). Disseminated intravascular coagulation is characterized by the widespread activation of coagulation, which results in the intravascular formation of fibrin and ultimately thrombotic occlusion of small and midsize vessels. "The patient developed dyspnea, hypotension, unremitting hyperthermia, tachycardia, and elevated serum myoglobin, and finally died of pyemia and disseminated intravascular coagulation." (PMID 35178478, 2022).
lactic acidosis (3 papers, 2012 to 2019). Metabolic acidosis characterized by the accumulation of lactate in the body. "From a mechanistic perspective, moderate lactic acidosis would decrease the affinity of myoglobin and hemoglobin for O2, thus facilitating O2 diffusion to muscle mitochondria for sustained oxidative phosphorylation during the apneic bouts." (PMID 23155452, 2012). "PPD attenuated lactic acidosis and reduced serum K+ and myoglobin levels in CI animals." (PMID 31319855, 2019). "Although PPD is useful for the correction of lactic acidosis and for the clearance of K+ and myoglobin, it failed to induce significant difference in survival rate as compared with controls (50% vs. 20%)." (PMID 31319855, 2019). "The lactic acidosis during reperfusion and after weaning from CPB was most likely a result of the initially reduced cardiac output of the transplanted organ, while the increase of serum creatine kinase and myoglobin were comparable to other major surgical procedures." (PMID 22973525, 2012).
leiomyosarcoma (3 papers, 2013 to 2025). An uncommon, aggressive malignant smooth muscle neoplasm, usually occurring in post-menopausal women. "In contrast to ERMS, leiomyosarcomas stain negatively for myoglobin and myogenin." (PMID 27357857, 2016). "In Fletchers’ 1992 retrospective review he used diagnostic criteria for leiomyosarcoma that included, co-expression of desmin and actin with myoglobin negativity and an absence of cross striations." (PMID 24216705, 2013). "Immunohistochemical analysis of the right ventricular outflow tract mass confirmed the presence of tumor cells that were positive for Desmin and smooth muscle actin (SMA), while negative for S-100 and myoglobin, leading to a diagnosis of leiomyosarcoma." (PMID 40556659, 2025). "In the case of the right ventricular outflow tract mass, immunohistochemistry confirmed the presence of tumor cells that exhibited positive staining for Desmin and SMA, while showing negative staining for S-100 and myoglobin, leading to a diagnosis of leiomyosarcoma." (PMID 40556659, 2025).
methemoglobinemia (3 papers, 2013 to 2022). An inherited or acquired condition characterized by abnormally increased levels of methemoglobin in the blood. "Myoglobin binds to NO through two different reactions, a direct interaction of MbO2 with NO, which then forms methemoglobinemia, and a nitrosylation of myoglobin deoxygenase (Mb), which then forms an intermediate compound of MbNO before reacting further with oxygen." (PMID 35178308, 2022). "Moreover, the self‐fuelled module can quickly recover the irreversibly oxidized methemoglobin (metmyoglobin) to the reduced hemoglobin (myoglobin), implying the potential for a new treatment to Methemoglobinemia and catalysing other redox reactions." (PMID 33427354, 2021).
Myocardial necrosis (3 papers, 2012 to 2020). Irreversible damage to heart tissue (myocardium) due to lack of oxygen after a heart attack (myocardial infarction). "Over the past 20 years, cardiac troponin (cTn), creatine kinase (CK)‐MB, and myoglobin have been the most commonly used cardiac biomarkers to identify myocardial necrosis in the evaluation of patients with suspected AMI." (PMID 28939707, 2017). "Furthermore, this miR-combination also led to higher AUC values than the combination of three myocardial necrosis markers (hs-troponin, myoglobin and CK-MB)." (PMID 23023917, 2012).
myonecrosis (3 papers, 2025). "While markedly elevated serum CK (peaked at 112,985 U/L) and myoglobin (>3,000 μg/L) were pathognomonic for severe myonecrosis, the transaminase profile was more complex." (PMID 40909457, 2025). "Although minor myonecrosis can occur routinely with partial regeneration, extensive muscle damage results in significant release of intracellular components, including myoglobin, into the circulation." (PMID 40635153, 2025).
amyotrophic lateral sclerosis (2 papers, 2021 to 2024). Amyotrophic lateral sclerosis (ALS) is a neurodegenerative disease characterized by progressive muscular paralysis reflecting degeneration of motor neurons in the primary motor cortex, corticospinal tracts, brainstem and spinal cord. "Neurofilament, myoglobin, and troponin T concentrations were higher in patients with amyotrophic lateral sclerosis compared to disease controls." (PMID 39239150, 2024). "Neurofilament concentrations were higher in classical amyotrophic lateral sclerosis than in progressive muscular atrophy, while myoglobin and troponin T levels were elevated in progressive muscular atrophy compared to primary lateral sclerosis." (PMID 39239150, 2024). "A recent study reported increased levels of myoglobin in the blood serum of patients with spinal and bulbar muscular atrophy but not in individuals with amyotrophic lateral sclerosis, suggesting that myoglobin is an appropriate biomarker for other neurological diseases." (PMID 34870700, 2021).
aortic valve insufficiency (2 papers, 2017 to 2023). Dysfunction of the aortic valve characterized by incomplete valve closure. "Generally, the risk of in‐hospital mortality rises with higher values of these continuous variables: HR, age, MB, left atrial diameter, left ventricular end‐diastolic diameter, right coronary stenosis, BNP, left main stenosis, CK‐MB, cTnI, and Killip class." (PMID 36479714, 2023).
asthma (2 papers, 2021 to 2024). "The underlying key genes in asthma pathogenesis and those regulated by treatment including Adipoq, HMOX1, SPP1, Cyp2e1, TNC, MB, MPO, Col9a1, Ckmt2, and Erbb4 were taken as examples to illustrate the positions and relationships with other points and midline in the figure." (PMID 33531915, 2021).
Cachexia (2 papers, 2012 to 2022). Severe weight loss, wasting of muscle, loss of appetite, and general debility related to a chronic disease. "MEF2C gene targets myozenin and myoglobin as well as myokinase were also altered during cachexia, suggesting dysregulated oxygen transport capacity and ATP regeneration in addition to distorted structural integrity." (PMID 22361433, 2012). "Additionally, myoglobin was positively related to quadriceps cross-sectional area (CSA) in both healthy individuals and patients with cachexia." (PMID 35334853, 2022).
delirium (2 papers, 2017 to 2023). A disorder characterized by confusion; inattentiveness; disorientation; illusions; hallucinations; agitation; and in some instances autonomic nervous system overactivity. "Again, delirium was associated mostly with higher expression, but the inverse was true preoperatively for myoglobin (MB), IL-2, and IL-20, and postoperatively for chemokine ligand 15 (CCL15) and TNF-related apoptosis-inducing ligand (TRAIL)." (PMID 37156856, 2023).
dermatomyositis (2 papers, 2012 to 2020). Dermatomyositis (DM) is a type of idiopathic inflammatory myopathy characterized by evocative skin lesions and symmetrical proximal muscle weakness. "Furthermore, in patients with dermatomyositis, serum resistin levels significantly correlated with MYOACT (r = 0.667, P = 0.001), creatine kinase (r = 0.739, P = 0.001) and myoglobin levels (r = 0.791, P = 0.0003) and showed a trend towards correlation with CRP levels (r = 0.447, P = 0.067)." (PMID 22577940, 2012).
embryonal rhabdomyosarcoma (2 papers, 2011 to 2023). A poorly circumscribed morphologic variant of rhabdomyosarcoma. "Patient 47 was initially diagnosed with an embryonal rhabdomyosarcoma but was found in our current analyses to be immunonegative for all of the tested muscle markers including desmin, myogenin, myoglobin, and myoD1." (PMID 37395142, 2023). "However, embryonal rhabdomyosarcoma is uncommon in patients older than 40 years of age and neither cross-striation nor myoglobin expression was proven in the present case." (PMID 21329505, 2011).
falciparum malaria (2 papers, 2012 to 2016). "Evidence of skeletal muscle damage in falciparum malaria has been found in both children and adults with serum CK and myoglobin concentrations paralleling clinical severity." (PMID 23256803, 2012).
glioma (2 papers, 2021 to 2025). A benign or malignant brain and spinal cord tumor that arises from glial cells (astrocytes, oligodendrocytes, ependymal cells). "In contrast, there is no specific enrichment with a FOXM1 antibody at the promoters of H19, myoglobin and CCND1 3 which are genes non-expressed or imprinted in glioma cells (they serve as negative controls)." (PMID 34131149, 2021).
head and neck squamous cell carcinoma (2 papers, 2022 to 2025). A squamous cell carcinoma that arises from any of the following anatomic sites: lip and oral cavity, nasal cavity, paranasal sinuses, pharynx, larynx, and salivary glands. "Interestingly, in head and neck squamous cell carcinoma, higher levels of myoglobin expression have been linked to a more favorable prognosis." (PMID 41378098, 2025).
Heat Stroke (2 papers, 2020 to 2021). A condition caused by the failure of body to dissipate heat in an excessively hot environment or during PHYSICAL EXERTION in a hot environment. "Typical serum indicators including CK and MB can be determined to specifically assess skeletal muscle injury; therefore, we measured the serum levels of these indicators from 0 to 24 h after the onset of heat stroke." (PMID 32655408, 2020).
Hematuria (2 papers, 2019 to 2025). The presence of blood in the urine. "So that the presence of erythrocytes, myoglobin and hemoglobin in the urine will give a positive result on the urine blood dipstick parameter which means hematuria occurs." (PMID 40417386, 2025). "So, the presence of erythrocytes, myoglobin or hemoglobin in the urine will give a positive result on the urine blood dipstick parameters, which means hematuria occurs." (PMID 40417386, 2025).
hyperglycaemia (2 papers, 2018 to 2021). "Due to the enhanced glucose uptake via glucose transporter 1 (GLUT1) in chronic hyperglycaemia, the amino group of myoglobin readily undergoes a non-enzymatic reaction which results in structural and functional changes of the myoglobin." (PMID 29419812, 2018).
hypertrophic cardiomyopathy (2 papers, 2017 to 2022). A condition in which the myocardium is hypertrophied without an obvious cause. "A previous study reported a several-fold rise in serum troponin, myoglobin and CK-MB concentrations after alcohol septal ablation for the treatment of hypertrophic cardiomyopathy." (PMID 36500700, 2022).
liver cirrhosis (2 papers, 2018 to 2024). "Thirdly, further investigations should analyze associations of ADC with muscle specific parameters like myoglobin and creatine kinase in liver cirrhosis." (PMID 30326652, 2018).
lung carcinoma (2 papers, 2021 to 2022). "Elevated levels of low-grade inflammation are accompanied by a concomitant decrease of myoglobin and increased atrogenes (i.e., MuRF1, Atrogin-1) in lung cancer models, that are involved in skeletal muscle degradation." (PMID 36067173, 2022).
microcytic anemia (2 papers, 2021 to 2026). Anemia in which the red blood cell volume is decreased. "Iron serves as a prosthetic group in hemoglobin and myoglobin, facilitating oxygen transport and cellular respiration, with deficiency resulting in microcytic anemia." (PMID 41523284, 2026).
myasthenia (2 papers, 2020 to 2023). "The patient was subsequently treated with meropenem combined with levofloxacin and sulbactam; her CPK and MB levels returned to normal, and the myasthenia was alleviated." (PMID 33120846, 2020).
myasthenia gravis (2 papers, 2020 to 2024). Myasthenia gravis (MG) is a rare, clinically heterogeneous, autoimmune disorder of the neuromuscular junction characterized by fatigable weakness of voluntary muscles. "CO’s high affinity for myoglobin may cause weakness in the lower esophageal sphincter, potentially leading to myasthenia gravis." (PMID 39618951, 2024).
ovarian carcinoma (2 papers, 2009 to 2020). A malignant neoplasm originating from the surface ovarian epithelium. "It is primarily considered a marker of muscle damage and the underlying biological role that myoglobin plays in ovarian cancer is unclear." (PMID 19240799, 2009). "Indeed, myoglobin levels do not appear to differ significantly between the ovarian cancer and control samples yet our analysis showed it has a relatively strong contribution to the classifier." (PMID 19240799, 2009).